PPIE (peptidylprolyl isomerase E)
Description:
Involved in pre-mRNA splicing as component of the spliceosome. Combines RNA-binding and PPIase activities. Binds mRNA and has a preference for single-stranded RNA molecules with poly-A and poly-U stretches, suggesting it binds to the poly(A)-region in the 3'-UTR of mRNA molecules. Catalyzes the cis-trans isomerization of proline imidic peptide bonds in proteins. Inhibits KMT2A activity; this requires proline isomerase activity.
Synonyms: CYP33; CyP-33; MGC3736; MGC111222; CypE
Tractability: Small molecule: a structure with a bound ligand is known; it has a binding pocket of medium quality. Antibody: its Gene Ontology location is reachable by antibodies, with high confidence. PROTAC: ubiquitination databases record sites on it; its protein half-life has been measured.
Target class: Isomerase; Enzyme
Gene: Protein-coding gene on chromosome 1 (39,692,182 to 39,763,914, forward strand). Ensembl gene ENSG00000084072.
Subcellular location: Nucleus
Subcellular location (Human Protein Atlas): Nuclear speckles
Pathways (Reactome):
DNA Repair: Dual incision in TC-NER; Formation of TC-NER Pre-Incision Complex; Gap-filling DNA repair synthesis and ligation in TC-NER; Transcription-Coupled Nucleotide Excision Repair (TC-NER)
Disease: Dengue Virus-Host Interactions
Immune System: Neutrophil degranulation
Metabolism of RNA: mRNA Splicing - Major Pathway
Gene Ontology:
Molecular function: mRNA binding; peptidyl-prolyl cis-trans isomerase activity; poly(A) binding; protein binding; RNA binding; cyclosporin A binding; nucleic acid binding
Biological process: mRNA splicing, via spliceosome; positive regulation of viral genome replication; regulation of DNA-templated transcription; protein folding
Cellular component: catalytic step 2 spliceosome; nuclear speck; nucleus; post-mRNA release spliceosomal complex; post-spliceosomal complex; spliceosomal complex; U2-type catalytic step 1 spliceosome; U2-type catalytic step 2 spliceosome; extracellular region; ficolin-1-rich granule lumen; nucleoplasm; secretory granule lumen; protein-containing complex
Genetic constraint (gnomAD): Loss-of-function variants: 19 observed, 36.12 expected, observed/expected ratio (o/e) 0.53, 90% interval 0.37 to 0.77. The upper end of that interval is the gene's LOEUF score, 0.77, which puts it in group 3 of 6, group 1 being the genes least tolerant of losing a copy. Missense variants: 316 observed, 397.07 expected, observed/expected ratio (o/e) 0.8, 90% interval 0.73 to 0.87. Synonymous variants: 141 observed, 141.78 expected, observed/expected ratio (o/e) 0.99, 90% interval 0.87 to 1.14.
Homologues: Orthologues: guinea pig PPIE (98% identical), mouse Ppie (98% identical), rabbit PPIE (98% identical), rat Ppie (96% identical), pig PPIE (95% identical), chimpanzee PPIE (93% identical), macaque PPIE (92% identical), zebrafish ppie (86% identical), tropical clawed frog ppie (85% identical), dog PPIE (81% identical), Drosophila melanogaster Cyp40 (29% identical), Caenorhabditis elegans cyn-9 (27% identical). Paralogues in human: PPIF (40% identical), PPIA (37% identical), PPIB (35% identical), PPID (34% identical), PPIAL4A (34% identical), PPIAL4C (34% identical), PPIAL4D (33% identical), PPIAL4E (33% identical), PPIAL4F (33% identical), PPIH (33% identical), PPIAL4G (33% identical), PPIAL4H (33% identical), and 10 more.
Diseases named in the same sentence as PPIE in open-access papers:
PPIE is named in the same sentence as 10 diseases in open-access papers, as found by Europe PMC text mining. Sharing a sentence is not in itself a finding about the gene and the disease. The quoted sentences say what the papers report.
ovarian carcinoma (2 papers, 2015 to 2021). A malignant neoplasm originating from the surface ovarian epithelium. "Furthermore, HNRNPC, CRNKL1, PNN and PPIE were also reported to have a high expression and biological function in several cancers including ovarian cancer 21-24." (PMID 33437214, 2021).
colorectal cancer (1 paper, 2016). A primary or metastatic malignant neoplasm that affects the colon or rectum. "PPIE belongs to the family of PPIases with proline isomerase activity that stimulates folding and conformational changes in proteins and may be linked to leukemia, colorectal cancer, and body mass index." (PMID 27903268, 2016).
PPIE also shares sentences with these, for which no sentence is quoted: cancer (2 papers); chronic lymphocytic leukemia (1); infection (1); influenza (1); leukemia (1); lymphoplasmacytic lymphoma (1); mastitis (1); viral infection (1).